ATXN3 (ataxin 3)
Diseases named in the same sentence as ATXN3 in open-access papers (continued):
Sharing a sentence is not in itself a finding about the gene and the disease.
Machado-Joseph disease (152 papers, 2008 to 2026). "For example, citalopram, a selective serotonin reuptake inhibitor, which elevates serotonin levels, protects mice expressing polyglutamine-containing disease protein Ataxin 3, which causes Machado Joseph Disease in humans." (PMID 41115589, 2025). "Machado-Joseph disease (MJD) is a neurodegenerative disease caused by an abnormally expanded polyglutamine tract in the ataxin-3 protein." (PMID 38332227, 2024). "This proteotoxic Ataxin 3 underlies the manifestation of the neurodegenerative disorder “Machado Joseph Disease” (MJD) in humans." (PMID 38016061, 2023). "Expansions in a CAG repeat region in ATXN3 cause Machado-Joseph disease, another progressive motor disorder." (PMID 38239833, 2023). "Spinocerebellar ataxia 3 (SCA3) is an autosomal dominant disorder caused by an abnormal CAG expansion mutation in the ATXN3 gene, and the most frequent SCA worldwide." (PMID 35087695, 2022). "MiRNA maturation is also impaired in models of expanded polyQ within ataxin-3 (causing Machado-Joseph disease), whereas blocking miRNA biogenesis increased ataxin-3 aggregation." (PMID 35869509, 2022). "SCA3, also known as Machado-Joseph disease, is caused by the expansion of CAG within ATXN3 that encodes ataxin-3." (PMID 35326260, 2022). "Proteolytic liberation of highly aggregation-prone polyQ fragments from the protective sequence of Ataxin-3 has been proposed to trigger the formation of Ataxin-3-containing aggregates, the neuropathological hallmark of Machado-Joseph disease." (PMID 32982735, 2020). "The MJD family name is derived from Machado-Joseph disease, a neurologic disorder caused by expansion of the polyglutamine tract in ataxin-3." (PMID 32647816, 2019). "In particular, misfolding and aggregation of the Josephin domain of ataxin-3 is implicated in spinocerebellar ataxia-3." (PMID 26215704, 2015). "Machado-Joseph disease (MJD) is an inherited neurodegenerative disease caused by an expanded CAG repeat in the ATXN3 gene." (PMID 25369462, 2014). "The C-terminus of the ataxin-3 protein contains a polyglutamine (PolyQ) region that, when mutationally expanded to over 52 glutamines, causes the neurodegenerative disease spinocerebellar ataxia 3 (SCA3)." (PMID 24293103, 2014). "In this study we demonstrate that p62 directly interacts with pathogenic Machado Joseph Disease (MJD)-associated protein ataxin-3 with polyglutamine (polyQ) expansion." (PMID 25158237, 2014). "In this study we show for the first time that allele-specific silencing of mutant ataxin-3 with lentiviral vectors robustly rescues Machado-Joseph disease behavioral and neuropathological phenotype in a severely affected transgenic mouse model." (PMID 23349684, 2013). "Detail will be given to the Machado-Joseph Disease-causative and polyQ-containing protein, ataxin-3, providing clues for the impact of polyQ expansion and its flanking regions in the modulation of ataxin-3 molecular interactions, function, and aggregation." (PMID 23801983, 2013). "Here, using a lentiviral-mediated allele-specific silencing of mutant ataxin-3 in an early pre-symptomatic cerebellar mouse model of Machado-Joseph disease we show that this strategy hampers the development of the motor and neuropathological phenotypic characteristics of the disease." (PMID 25144231, 2014). "Misfolding- and aggregation-prone proteins underlying Parkinson's, Huntington's and Machado-Joseph diseases, namely α-synuclein, huntingtin, and ataxin-3 respectively, adopt numerous intracellular conformations during pathogenesis, including globular intermediates and insoluble amyloid-like fibrils." (PMID 19492089, 2009). "Machado-Joseph disease (MJD) is a neurodegenerative disorder triggered by mutant ataxin-3 protein that causes protein misfolding and aggregation resulting in neuronal death." (PMID 40374597, 2025).
Machado-Joseph disease (continued). "Machado-Joseph disease (MJD) is an autosomal dominant spinocerebellar ataxia (SCA) caused by a polyglutamine expansion in the ataxin-3 protein, which initiates a cascade of pathogenic events, including transcriptional dysregulation." (PMID 38900099, 2024). "Machado-Joseph disease (MJD) is a dominant neurodegenerative disease caused by an expanded CAG repeat in the ATXN3 gene encoding the ataxin-3 protein." (PMID 37408238, 2023). "In SCA3 (also known as Machado-Joseph disease or MJD), the ataxin-3 gene is mutated and typically contains an extension with 60-87 CAG-repeats." (PMID 27469193, 2016). "We are interested in elucidating the underlying mechanisms of toxicity of the protein ataxin-3, in which a polyglutamine expansion is the genetic determinant for Machado-Joseph Disease (MJD), also referred to as spinocerebellar ataxia 3 (SCA3)." (PMID 24817148, 2014). "In a study on Machado-Joseph disease, ataxin-3 (ATX-3) was found to block the transfer of Ub from E2 ubiquitin ligase to E3 ubiquitin ligase, thereby disrupting the ubiquitin cascade reaction." (PMID 39609371, 2025). "Ataxin-3, which is associated with Machado–Joseph disease (MJD) or spinocerebellar ataxia-3 (SCA3), functions as a deubiquitinating enzyme (DUB) that primarily cleaves Lys-63 linkages." (PMID 39940735, 2025). "The expression of human ATXN3 with 10 CAG repeats, below the threshold to cause Machado-Joseph disease, in C. elegans GABAergic neurons under the unc-47 promoter results in motor deficits and reduced lifespan, but not neurodegeneration." (PMID 38239833, 2023). "Ataxin-3, the protein responsible for spinocerebellar ataxia 3 (SCA3), has multiple phosphorylation sites and specific phosphorylation patterns can decrease or increase its aggregation." (PMID 36009526, 2022). "These include ATXN3 and OTUD5, respectively, causing the Machado-Joseph disease and a X-linked multiple congenital anomalies-neurodevelopmental syndrome." (PMID 34566579, 2021). "Ataxin-3 contains an N-terminal Josephin domain (JD), a conserved module named after the Machado-Joseph disease, two ubiquitin interacting motifs (UIMs), a polyQ stretch, and a flexible variable tail." (PMID 32982735, 2020). "Ataxin-3 fragments can be found in brain tissues of Machado-Joseph disease patients and mice expressing mutant Ataxin-3 (Q71)." (PMID 32982735, 2020). "As a therapeutic target in neurodegenerative disease, Ataxin-3 has been well characterized in the progression of Machado-Joseph disease." (PMID 32982735, 2020). "SCA3/Machado-Joseph disease (MJD) is caused by CAG repeated amplification of the ATXN3 gene." (PMID 31275113, 2019). "SCA3 (also called Machado-Joseph Disease, MJD), is caused by CAG repeat expansion in the ATXN3-encoding gene." (PMID 30283301, 2018). "SCA3, also known as Machado-Joseph disease, is the most common subtype of SCAs in China, which is caused by an abnormal CAG trinucleotide repeat expansion in ATXN3 gene." (PMID 25354658, 2015). "Machado-Joseph disease (MJD) is an inherited neurodegenerative disease, caused by a CAG repeat expansion within the coding region of ATXN3 gene, and which currently lacks effective treatment." (PMID 26505994, 2015). "Expansion of the polyQ repeat that resides in ataxin-3 are the underlying cause for the most common form of autosomal dominant SCA, known as SCA-3 or Machado-Joseph disease." (PMID 25132814, 2014). "The presence of ataxin-3 in the nucleus has been shown to drastically aggravate the pathology in Machado-Joseph disease." (PMID 23349684, 2013). "For example, we have reported a beneficial effect of autophagy on clearance of ataxin-3, the protein responsible for SCA3, also known as Machado-Joseph disease, the most common type of SCA." (PMID 21930185, 2012). "One of the putative players in the protein quality control pathway is the polyQ protein ataxin-3, involved in Machado-Joseph disease." (PMID 21526185, 2011).
Machado-Joseph disease (continued). "Ataxin-3, the protein involved in Machado-Joseph disease, is able to bind ubiquitylated substrates and act as a deubiquitylating enzyme in vitro, and it has been involved in the modulation of protein degradation by the ubiquitin-proteasome pathway." (PMID 21526185, 2011). "Modification of one polyglutamine disease (e.g. Huntington’s disease) by the repeat length of another (e.g. ATXN3, CAG expansions in which cause spinocerebellar ataxia 3) has also been hypothesized." (PMID 38449714, 2024). "Interestingly, UBE4B has been found to poly-ubiquitinate an abnormal form of ataxin-3 which is responsible for the development of Machado-Joseph disease, thereby marking it for degradation by the ubiquitin-proteasome pathway." (PMID 31878315, 2019). "In this work we have employed molecular modelling techniques to shed light into conformational dynamics and kinetics of the Josephin Domain, part of the protein Ataxin 3, which is responsible for the spinocerebbellar ataxia 3, also called Machado Joseph Disease." (PMID 26745628, 2016). "While Ataxin-3 predominantly localizes within the nuclei of neurons in Machado-Joseph Disease (MJD), this small soluble protein can shuttle between the nucleus and cytoplasm." (PMID 38233440, 2024). "SCA type 3 (SCA3), also known as Machado-Joseph disease, caused by abnormal CAG trinucleotide expansion greater than 62 at the gene of ataxin-3, is the most frequent SCA in most countries." (PMID 37817286, 2023). "Overall, our data highlight the relevance of lysine residues 8 and 85 of ataxin-3 and encourage further analyses, to evaluate the potential of modulating posttranslational modifications of these sites for influencing pathophysiological characteristics of the Machado-Joseph disease protein." (PMID 37273907, 2023). "Spinocerebellar ataxias type 3 (SCA3), also known as Machado-Joseph disease, is the most common type of SCAs worldwide caused by CAG expansion of ATXN3 gene." (PMID 33468086, 2021). "Spinocerebellar ataxia 3, also known as Machado-Joseph disease (SCA3/MJD), is a rare autosomal-dominant neurodegenerative disease caused by an abnormal expansion of CAG repeats in the ATXN3 gene." (PMID 31316347, 2019). "UBE4B has been found to be associated with the poly-ubiquitination of an abnormal form of ataxin-3, which has been shown to be responsible for the development of Machado-Joseph disease (MJD)." (PMID 31878315, 2019). "This includes α-synuclein in PD or transactivation response element DNA-binding protein 43 (TDP-43) in ALS, as well as the polyQ disease proteins huntingtin in Huntington disease (HD) and ataxin-3 in Machado-Joseph disease (MJD)." (PMID 30895192, 2019). "The genetic basis of MJD/SCA3 is an expansion of the polyglutamine (PolyQ) tract of ataxin-3 (also known as Machado-Joseph Disease protein; MJD)." (PMID 24039611, 2013). "Machado-Joseph disease (MJD/ATXN3) is an autosomal dominant progressive neurologic disorder characterized primarily by ataxia, spasticity, and ocular movement abnormalities." (PMID 18927607, 2008). "Machado-Joseph disease (MJD, also known as spinocerebellar ataxia type-3) is a fatal disease characterised by motor impairments and the presence of aggregated ataxin-3, the protein affected in MJD, in degenerating brain regions." (PMID 41493127, 2026). "The most frequent SCA worldwide are those caused by CAG repeat expansions, as SCA1 (in ATXN1), DRPLA (ATN1), SCA2 (ATXN2), Machado-Joseph disease (MJD)/ SCA3 (ATXN3), SCA6 (CACNA1A), SCA7 (ATXN7), and SCA17 (TBP), usually designated polyglutamine (polyQ) ataxias." (PMID 39048885, 2024). "In Machado-Joseph disease (MJD), a neurodegenerative disease with an abnormal expansion of the CAG triplet in the ATXN3 gene, resveratrol elevated the SIRT1 expression to improve motor deficits." (PMID 33809718, 2021).
Machado-Joseph disease (continued). "Moreover, mutant type Ataxin-3 promotes the clearance of parkin via the autophagic degradation of parkin, raising the possibility that elevated turnover of parkin may be the partial reason of Machado-Joseph disease." (PMID 32982735, 2020). "The most common SCA, Machado-Joseph disease (MJD/SCA3), caused by mutated ataxin-3 gene (ATXN3), has no treatment currently available." (PMID 41818480, 2026). "The ATXN3 variant reflects the variability of the CAG repeat region of this gene—frameshifts here are common and the insertion length did not approach the threshold for a pathological triplet repeat expansion as found in Machado-Joseph disease (which would also not match the proband’s presentation)." (PMID 37048120, 2023). "Human ataxin-3, a DUB, is involved in Machado-Joseph disease (MJD)." (PMID 36237424, 2022). "However, it is highly likely that ATX3 deficiency exert its pathogenic effect independent of its deubiquitination function, since Machado-Joseph disease is a triplet (CAG encoding glutamine, Q) repeat expansion disorder whereby ATXN3 mutant proteins accumulate as toxic insoluble protein aggregates." (PMID 34566579, 2021). "Ataxin-3 (AT3) is a polyglutamine (polyQ)-containing protein that is related to one kind of the polyQ diseases, spinocerebellar ataxia 3 or Machado-Joseph disease (SCA3/MJD)." (PMID 20949063, 2010).
Huntington disease (66 papers, 2005 to 2026). Huntington disease (HD) is a rare neurodegenerative disorder of the central nervous system characterized by unwanted choreatic movements, behavioral and psychiatric disturbances and dementia. "Gene Set Enrichment Analysis analysis associated ATXN3 with immune regulation, interferon signaling, Huntington’s disease pathways, and chromosomal organization." (PMID 41507147, 2026). "It is believable that de novo mutations of ATXN3 exist since they have been found in some other dynamic mutation diseases such as Huntington’s disease (HD; MIM# 143100), SCA2 (MIM# 183090), SCA7 (MIM# 164500) and SCA17 (MIM# 607136)." (PMID 26266536, 2015). "PolyQ-expanded Ataxin-2 abundance in biofluids would be an obvious candidate biomarker for SCA2, similar to what was described for huntingtin or Ataxin-3 proteins in Huntington ́s disease (HD) or SCA3, respectively." (PMID 41298695, 2025). "In a Drosophila model of Huntington's disease, co-expression of wild-type ataxin-3 and polyQ-expanded htt resulted in complete restoration of the neurodegeneration that is typically observed with expression of pathogenic htt alone." (PMID 38497605, 2024). "Similar to Huntington's disease, downregulation of the mutant transcript is regarded as a promising treatment strategy for SCA3, as the ATXN3 transcript is the most upstream target in the pathological cascade underlying the disease." (PMID 34878314, 2022). "In fact, ATXN3 has been shown to work with HTT, the mutated protein in Huntington’s disease, in a transcription-coupled repair (TCR) complex to repair DNA strand breaks." (PMID 36010688, 2022). "With respect to ATXN3, the recent identification of Huntingtin, the polyQ protein responsible for Huntington's disease, as a substrate adaptor for autophagy, appears to be most relevant." (PMID 31625269, 2020). "These authors focus on ataxin-3 and huntingtin (Htt), the main protein implicated in Machado–Joseph Disease (MJD) and Huntington’s disease (HD) respectively." (PMID 24348458, 2013). "Additional analysis focusing specifically on ATXN3 in a larger sample set (n = 1388) confirmed the lack of association between Huntington’s disease residual age-at-onset and ATXN3 CAG repeat length." (PMID 38449714, 2024). "Consistent with observations in Huntington disease, transgenic SCA3 mice reveal a tendency for decrease of soluble mutant ataxin-3 during disease progression in fractions of the cerebellum, which is inversely correlated with aggregate formation and phenotypic aggravation." (PMID 23626768, 2013). "Although there is no direct evidence for SCA1, activation of glucocorticoid receptors seems to attenuate the aggregation of polyQ-expanded ataxin-3 and huntingtin proteins in SCA3 and Huntington’s disease (HD), respectively." (PMID 40029919, 2025). "But, in a recent publication lack of ataxin-3 did not seem to enhance pathology in a Huntington's Disease mouse model." (PMID 25191222, 2014).
Parkinsonism (43 papers, 2008 to 2026). Characteristic neurologic anomaly resulting from degeneration of dopamine-generating cells in the substantia nigra, a region of the midbrain, characterized clinically by shaking, rigidity, slowness of movement and difficulty with walking and gait. "Short tandem repeat analysis also identified ATXN3 CAG repeat expansions within the pathogenic range (CAGn > 45) in three patients with Parkinson's disease of African ancestry." (PMID 41058593, 2026). "The E3 ubiquitin ligase parkin, whose mutations are notoriously associated with juvenile manifestations of Parkinson’s disease, is one of the prime binding partners of ataxin-3, linked to its role within the ubiquitin system." (PMID 39088078, 2024). "Interestingly, MJD can present with clinical and neuropathological symptoms of Parkinson disease (PD), and this raises the possibility that an interaction between ataxin-3 and a PD-associated protein could be involved in MJD." (PMID 23653622, 2013). "Mutations in ATXN3, PRNP, and CACNA1A have been implicated in PD and parkinsonism through diverse mechanisms and clinical presentations in isolated cases." (PMID 41009775, 2025). "Although both ATXN3-WT and ATXN3-PolyQ can deubiquitinate the E3 ligase Parkin, associated with PD, ATXN3-PolyQ increases the turnover of Parkin, which could possibly contribute to some of the Parkinson-like features in SCA3." (PMID 39320846, 2024). "Therefore, we analysed missense single nucleotide polymorphism variants in the PRKN gene encoding the Parkinson's disease-associated E3 ubiquitin ligase parkin, which is a well-described interaction partner of the MJD protein ataxin-3, a deubiquitinase." (PMID 39088078, 2024). "The interactions of ataxin-3 with the UblP37L and pUblP37L domains were also examined to identify how a Parkinson's disease–substituted parkin combined with phosphorylation might further alter this interaction." (PMID 29530980, 2018).
dentatorubral-pallidoluysian atrophy (42 papers, 2005 to 2025). Dentatorubral pallidoluysian atrophy (DRPLA) is a rare subtype of type I autosomal dominant cerebellar ataxia (ADCA type I). "We inferred neutral evolution for the three other microsatellites causative of the trinucleotide expansion disorders SCA3 (ATXN3), dentatorubral-pallidoluysian atrophy (DRPLA) (ATN1), and myotonic dystrophy type 1 (DM1) (DMPK)." (PMID 39775235, 2024). "Genes that were part of this signature on the brain side were the TCF4, ATN1, PPP2R2B, ATXN10 and ATXN3, which are associated with neurodegenerative and developmental disorders such as Pitt-Hopkins Syndrome, Dentatorubral pallidoluysian atrophy, SCA12, SCA10 and SCA3." (PMID 27476530, 2016). "Using similar structure probing approaches, several “slipped” hairpin variants have been observed for CAG repeats of the atrophin (ATN1), ATXN2, and ATXN3 transcripts, which are implicated in dentatorubral-pallidoluysian atrophy (DRPLA), SCA2 and SCA3, respectively." (PMID 28442996, 2017).